EPCAM (epithelial cell adhesion molecule)
Diseases named in the same sentence as EPCAM in open-access papers (continued):
Sharing a sentence is not in itself a finding about the gene and the disease.
colorectal cancer (259 papers, 2003 to 2026). A primary or metastatic malignant neoplasm that affects the colon or rectum. "Currently, EpCAM has been FDA-approved as a diagnostic marker for breast, prostate, and colorectal cancers, and anti-EpCAM monoclonal antibodies have been approved in Europe for treating malignant ascites in EpCAM-positive cancer patients." (PMID 41357552, 2025). "Lynch syndrome (LS) is an autosomal dominant disorder caused by germline mutations in mismatch repair (MMR) genes or EpCAM, leading to various cancers, particularly colorectal cancer (CRC)." (PMID 41164816, 2025). "EpCAM (CD326) was one of the first human tumor-associated antigens (TAA) discovered with monoclonal antibodies more than forty years ago in patients with colorectal carcinomas." (PMID 36845124, 2023). "Epithelial Cell Adhesion Molecule (EpCAM) is overexpressed in colorectal cancer cells and strongly associated with cancer development." (PMID 35281893, 2022). "Studies have shown that the presence of the epithelial cell adhesion molecule (EpCAM) in exosomes has diagnostic value for colorectal cancer, while other markers in exosomes such as the EGFR subtypes can predict the efficacy of treatments for glioblastoma." (PMID 36140089, 2022). "The cumulative risk by the age of 70 years of EC in women with EPCAM deletions was 12% and that of colorectal cancer in EPCAM deletion carriers was 75%." (PMID 35311082, 2022). "The loss of EPCAM was reported in Lynch syndrome cancers and germline deletion of this gene was associated with predisposition to colorectal cancer in Lynch syndrome." (PMID 27047543, 2016). "Epithelial cell adhesion molecule (EpCAM) is known to be overexpressed in epithelial cancers associated with enhanced malignant potential, particularly colorectal carcinoma (CRC) and head and neck squamous cell carcinoma (HNSCC)." (PMID 26317650, 2015). "What is interesting, high expression of EPCAM in colorectal cancer stem cells answers the question of why carriers with an EPCAM 3’ end deletion have a substantially increased risk of colon cancer." (PMID 23938213, 2013). "Elevated levels of EpCAM are associated with poor prognosis in colorectal cancer patients." (PMID 40316530, 2025). "Therefore, combining EpCAM assessment with other diagnostic factors is crucial for diagnosing colorectal cancer effectively." (PMID 41357552, 2025). "Similarly, EpCAM and claudin-7 associated via intracellular cytoplasmic tails in pancreatic adenocarcinoma and colorectal cancer cells." (PMID 32091301, 2020).
colorectal cancer (continued). "Epithelial Cell Adhesion Molecule (EpCam)-based capturing of exosomes for miRNA detection has been reported for colorectal cancer, and there are some concerns about the loss of EpCam presence in epithelial cell–derived cancer cells because of no (or low) expression or cleavage of EpCam." (PMID 28672799, 2017). "Furthermore, claudin-7, CD44 variant 6, EpCAM and the tetraspanin CP-029 appear to be upregulated in colorectal cancer with liver metastasis and form a common complex in regions termed tetraspanin-enriched membrane microdomains (TEM)." (PMID 26243458, 2016). "Our data shows that EPCAM itself could be also susceptible to methylation in a small subset of Lynch syndrome-related colorectal cancers." (PMID 27047543, 2016). "However, the results we obtained using serial sections of aCP are in line with reports of budding cells in colorectal carcinomas, where the loss of membranous EpCAM was described in cells with nuclear translocation of β-catenin." (PMID 27431859, 2016). "In colorectal cancer (CoCa) EpCAM is frequently associated with claudin-7." (PMID 25514462, 2015). "Notably, in support of our findings, loss of membranous EpCAM has been significantly associated with the presence of lymph node metastasis in colorectal cancer as well." (PMID 23153310, 2012). "Indeed, in colorectal carcinoma, EpCAM and claudin-7 are found in association with the tetraspanins CD9 and/or CO-029 and promote metastasis formation." (PMID 21789222, 2011). "We here show that such mutated colorectal cancer cells are highly sensitive to lysis by an EpCAM-specific T cell-engaging antibody, suggesting that redirected lysis by T cells is not affected by mutations in intracellular signaling proteins of the EGFR pathway." (PMID 20976159, 2010). "EpCAM, another key surface glycoprotein overexpressed in colorectal cancer but minimally expressed in normal epithelia, has also been widely investigated." (PMID 41560835, 2026). "This study highlights the critical roles of NAG-1/GDF15, EpCAM, β-catenin, and NF-κB in the pathophysiology of colorectal cancer (CRC)." (PMID 40316530, 2025). "For example, BC200 lncRNA is overexpressed in colorectal cancer cells and is located adjacent to the oncogene EpCAM." (PMID 40251829, 2025). "created an EpCAM-specific second-generation CAR- NK-92 that effectively recognized EpCAM-positive colorectal cancer cells and released key cytokines, showcasing specific cytotoxicity in vitro." (PMID 40260240, 2025). "Due to its high expression levels on the cell surface, EpCAM has become a key target for immunotherapy in colorectal cancer, prompting the development of various therapeutic strategies." (PMID 40316530, 2025). "In colorectal cancer, EpCAM+ cells represent a typical epithelial phenotype, whereas EpCAM− cells exhibit mesenchymal features and higher metastatic potential." (PMID 40665579, 2025). "EpCAM, initially identified in colorectal cancer cell lines, is a membrane-bound protein with oncogenic properties." (PMID 40316530, 2025). "GQDs with zeolitic imidazolate framework-8 (ZIF-8), functionalised with PEG and epithelial cell adhesion molecule (EpCAM), were developed and targeted against colorectal cancer." (PMID 40075725, 2025). "Another related clinical trial (NCT03013712) focused on EpCAM CAR-T for the treatment of EpCAM-positive solid tumors (gastric cancer, colorectal cancer)." (PMID 40097979, 2025). "In this study, we utilized flow cytometry to evaluate the expression levels of the EpCAM gene across seven colorectal cancer cell lines, revealing inconsistent expression levels." (PMID 41357552, 2025).
colorectal cancer (continued). "Our results yielded successful development of EpCAM-overexpressing colorectal cancer cell lines, HT-29-OE-EpCAM-2 (73.63%) and HT-115-OE-EpCAM-19 (24.06%)." (PMID 41357552, 2025). "Researchers engineered EpCAM-targeted CAR-NK cells, which exhibited specific cytotoxicity against EpCAM-positive human colorectal cancer cell lines, namely, HCT-8 and HCT-116." (PMID 40705122, 2025). "In colorectal cancer, EpCAM is frequently overexpressed, leading to enhanced tumor cell growth, invasion, and metastasis." (PMID 40316530, 2025). "This study not only provides essential tools for researching the EpCAM gene’s role in colorectal cancer but also establishes a strong foundation for targeted therapy and immunotherapy research." (PMID 41357552, 2025). "EpCAM-specific monoclonal antibodies (mAbs) have been used in treating human colorectal cancer since 1900, with a 30% increase in five-year survival and a 27% reduction in recurrence rates within 7 years of treatment." (PMID 39911266, 2025). "Initially, EpCAM was found ubiquitously and strongly expressed on the surface of various epithelial cancer cells, in particular in prostate, pancreatic, and colorectal cancers." (PMID 38791091, 2024). "These interactions imply that the aptamer functionalized nanoparticles can specifically bind to the EpCAM protein overexpressed in colorectal cancer tissue for the site-specific delivery of the drug." (PMID 39164686, 2024). "This study constructed a third-generation EpCAM-CAR targeting colorectal cancer antigen EpCAM using scFv from the EpCAM monoclonal antibody as an extracellular single-chain variable region." (PMID 39107717, 2024). "Among these, ZEB1, SPARC, CDH1 and EpCAM were the most significantly differentially expressed genes between TRPS1-WT and TRPS1-MT cells and had been previously associated with colorectal cancer metastasis." (PMID 39307879, 2024). "In colorectal cancer (CRC), EpCAM has been implicated in the Wnt signaling pathway, as EpICD and β-Catenin are coordinately translocated to the nucleus." (PMID 39010070, 2024). "LDH release assays revealed that CAR-NK-92 cells exhibited enhanced killing ability against EpCAM-positive colorectal cancer cells at various E:T ratios of 40:1, 20:1, 10:1, 5:1, and 1:1." (PMID 38694508, 2024). "Earlier studies have indicated that promoter methylation does not play a major role in regulating EpCAM expression in breast and colorectal cancers, implying multiple mechanisms for EpCAM expression regulation." (PMID 38791091, 2024). "In this study, a third-generation EpCAM-CAR was designed against colorectal cancer-specific antigen EpCAM and successfully constructed by lentiviral infection into T cells, and the effectiveness of this EpCAM-CAR-T cell was verified both in vitro and in vivo." (PMID 39107717, 2024). "Using this method, we successfully created several new generations of colorectal cancer cell lines with monoallelic and biallelic knockouts of the epithelial cell adhesion molecule (EpCAM) gene." (PMID 39541329, 2024). "The levels of miR-23a-3p in circulating EpCAM+ extracellular vesicles (EVs) were increased in colorectal cancer patients compared to healthy controls and they then decreased after surgery." (PMID 38397007, 2024). "It has also been investigated as a therapeutic target, and clinical trials of anti-EPCAM monoclonal antibodies have been conducted in colorectal cancer and metastatic breast cancer." (PMID 38291183, 2024). "Epithelial-specific adhesion molecule (EpCAM) is a 40 kD type I transmembrane glycoprotein, functioning not only as a cancer stem cell antigen but also as a specific antigen for colorectal cancer." (PMID 39107717, 2024). "These investigations establish a fundamental research foundation for the clinical application of CAR-T treatment targeting the EpCAM antigen in colorectal cancer." (PMID 39107717, 2024).
colorectal cancer (continued). "Compared with healthy tissues, higher levels of EpCAM-positive exosomes are detected in the blood of patients with lung cancer and colorectal cancer." (PMID 38791091, 2024). "We aimed to generate HCT-116 cell lines containing biallelic knockouts of the EpCAM gene, which has a significant expression in colorectal cancer (CRC) and established oncogenic characteristics." (PMID 39541329, 2024). "The role of EpCAM in cancer was first elucidated in 1979, when it was described as a tumor antigen in colorectal carcinomas." (PMID 38612911, 2024). "Specifically, biotinylated anti‐human EpCAM antibody was used to capture EVs derived from carcinoma cells, for example, HT‐29 colorectal carcinoma cells." (PMID 39221546, 2024). "Epithelial cell adhesion molecule (EpCAM) is known to highly expression and promotes cancer progression in many cancer types, including colorectal cancer." (PMID 37543570, 2023). "After which, successful immunostaining of the intrahepatic microvasculature using panendothelial cell antigen MECA-32 and colorectal cancer cells using epithelial cell adhesion molecule (EpCAM) was established." (PMID 37077833, 2023). "The epithelial cell adhesion molecule (EpCAM) is often overexpressed in many types of tumors, including colorectal cancer." (PMID 37345198, 2023). "EpCAM plays an important role in colorectal cancer biology and is also involved in survival signaling, motility, differentiation, cell proliferation, adhesion, and metastasis." (PMID 37345198, 2023). "We propose the potential crosstalk of EpCAM signaling with the HGFR signaling in order to govern metastatic activity in colorectal cancer." (PMID 37543570, 2023). "The expression level of EpCAM corelated with prognosis and metastasis of colorectal cancer, CAR T cells targeting EpCAM selectively destroy cancer cells with high EpCAM expression." (PMID 36369033, 2022). "Blood concentrations of total, CD133+ and EPCAM+ EVs were determined in a cohort of patients with colorectal cancer (n = 54) and in a group of age and sex-matched HCs (n = 48)." (PMID 35267665, 2022). "CSCs are characterized by expression of surface markers that includes CD133, CD44 and EpCAM which are of specific relevance to colorectal cancer." (PMID 35642021, 2022). "It was bound to maleimide-DTPA (as a chelating agent) and gadolinium (Gd) to create the anti-EpCAM-Gd-DTPA and proved to be an effective in vitro MRI contrast agent, specifically in the diagnosis of colorectal cancer and other EpCAM-positive tumors." (PMID 36077739, 2022). "On the other hand, the EpCAM is overexpressed in a wide range of tumors, including colorectal cancer." (PMID 36153626, 2022). "Most studies using FC in CTC detection were performed in blood samples from colorectal cancer patients with standard epithelial markers, such as EpCAM, K20, K5/6/8/17, and EpCAM/pan-K used for CTC identification." (PMID 36077716, 2022). "Lynch syndrome (LS) is an inherited genetic condition associated with increased predisposition to colorectal cancer (CRC) and other tumors and is caused by germline mutations in Mismatch Repair (MMR) or EPCAM genes." (PMID 35223509, 2022). "Monoclonal antibodies to EpCAM were described to induce antibody-dependent cellular cytotoxicity in colorectal cancer therapy." (PMID 36011331, 2022). "Epithelial cell adhesion molecule (EpCAM) is a glycoprotein expressing on the surface of epithelial cell and several tumor types, including colorectal cancer, endometrial carcinoma, lung carcinoma, gastric cancer, and BC." (PMID 34983878, 2022). "Epithelial marker EpCam was positive throughout the whole tumoroid, indicating that it consisted of colorectal cancer cells of epithelial origin." (PMID 35624293, 2022). "Epithelial cell adhesion molecule (EpCAM) and human epidermal growth factor receptor 2 (HER2) are transmembrane glycoprotein receptors associated with colorectal cancer." (PMID 35757741, 2022).
colorectal cancer (continued). "EpCAM is a type-1 transmembrane glycoprotein that was initially considered a tumor antigen in colorectal carcinoma." (PMID 35361871, 2022). "GA733-2 is known to be a colorectal carcinoma antigen and an epithelial cell adhesion molecule (synonyms: EpCAM, TACSTD1, MIC18 and M4S1)." (PMID 35697846, 2022). "We revealed the potential of the CD44v6 as a complementary marker to EpCAM to detect and purify CTCs in colorectal cancer blood samples." (PMID 34638450, 2021). "At the final stage, an epithelial cell adhesion molecule (EpCAM) aptamer as an active targeting moiety was covalently attached (Apt-PEG-Au@NPs-DOX) for selective drug delivery to colorectal cancer (CRC) cells." (PMID 34641857, 2021). "TAMs and EpCAM+CD44+ colorectal cancer cells were isolated from human tumor-derived colorectal cancer xenografts, and then cancer cells were inoculated into nude mice with or without TAMs." (PMID 34209679, 2021). "Among TAAs, glycoprotein GA733, or epithelial cell adhesion molecule (EpCAM), is highly expressed on the surface of colorectal cancer cells and has been extensively investigated." (PMID 33868796, 2021). "Such “switch-on” and enhancement fluorescence profiling was shown to distinguish healthy from colorectal cancer patient samples using either CD63 or EpCAM." (PMID 34855021, 2021). "Accordingly, various studies using α-amanitin-conjugated anti-epithelial cell adhesion molecule (EpCAM) antibody in murine models suggest their interest in colorectal cancer, pancreatic carcinomas, and various EpCAM-expressing malignancies." (PMID 34208167, 2021). "TINCR overexpression inhibits the proliferation and metastasis of colorectal cancer cells by promoting EpCAM cleavage." (PMID 34187411, 2021). "Due to its high antigenicity and expression, EpCAM has been a target of monoclonal antibody therapies in colorectal cancer." (PMID 34209658, 2021). "Detection of EpCAM positive CTCs has provided prognostic information in breast, liver, prostate, colorectal cancer, and neuroendocrine cancer patients." (PMID 34209658, 2021). "Epithelial cell adhesion molecule (EpCAM) is a transmembrane glycoprotein that was discovered in colorectal cancer cells 40 years ago." (PMID 33691694, 2021). "In colorectal cancer for example, the proteolytic cleavage of membrane-bound EpCAM leads to the liberation of its intracellular domain (EpICD) into the cytoplasm." (PMID 32046162, 2020). "The evaluation of colorectal cancer and liver metastasis patients showed that complex formation of the EpCAM, claudin-7, CO-029, and CD44v6 was correlated with clinical data." (PMID 32091301, 2020). "For example, nanoplatforms have been developed, which can specifically target colorectal cancer cells via an EpCAM antibody-functionalization representing an in vitro model for CTC targeting in colorectal cancer patients." (PMID 32098406, 2020). "In conclusion, the transgenic Chinese cabbage expressing EpCAM–IgM Fc can be applied to express anti-colorectal cancer IgM Fc fusion recombinant vaccine candidate proteins." (PMID 33143243, 2020). "EpCAM was first described in 1979 as a humoral antigen recognized by monoclonal antibody 1083-17-1A (Co17-1A or mAb 17-1A) following inoculation of human colorectal cancer cells in mice." (PMID 32507912, 2020). "The activity of MT110 is strongly dependent on EpCAM expression, and the most frequent EpCAM expression in colorectal cancers makes it a good candidate for this treatment." (PMID 32533270, 2020). "There is ample evidence for the complex of cell adhesion molecules, EpCAM and claudin-7, and a tetraspanin, promoting colorectal cancer progression." (PMID 32091301, 2020). "Synergistic effects of regorafenib and EpCAM CAR NK-92 cells were analyzed in a mouse model with human colorectal cancer xenografts." (PMID 33101285, 2020).